IL22 (interleukin 22)
Diseases named in the same sentence as IL22 in open-access papers (continued):
Sharing a sentence is not in itself a finding about the gene and the disease.
cancer (166 papers, 2011 to 2025). A tumor composed of atypical neoplastic, often pleomorphic cells that invade other tissues. "IL-22 has been associated via Stat3 activation with cancer-promoting properties in several types of cancer, including HCC, LC, and PC." (PMID 40806452, 2025). "Several studies have demonstrated that IL-20, IL-22, and IL-24 are involved in the regulation of programmed cell death by apoptosis and/or autophagy, widely implicated as physiological barriers to cancer development." (PMID 40806452, 2025). "A growing number of studies indicate both the protective and pathogenic properties of IL-22 in various diseases, including cancer initiation and progression." (PMID 40729006, 2025). "To maximise beneficial effects whilst reducing the risk of epithelial proliferation and cancer, we designed short-acting IL-22-bispecific biologic drugs that successfully targeted the liver and pancreas." (PMID 38811532, 2024). "Alternation in the expression of interleukins such as IL-17, IL-22, and IL-1ß has been associated with various types of cancer." (PMID 37176567, 2023). "The majority of ILC3’s functions are associated with the release of cytokines, primarily IL-22 in cancer, but also IL-17 and other molecules." (PMID 36341381, 2022). "The emergences of IL-22-expressing cancer-associated fibroblasts and immunofibroblats enhance the complexity of IL-22 production." (PMID 35911703, 2022). "In fact, N8-acetylspermidine, which strongly induced IL-8 and IL-22, promoted cancer cell proliferation and inhibited cancer cell death caused by the anticancer drug oxaliplatin." (PMID 33430687, 2021). "IL-22 has been revealed to act as a pro-tumor cytokine in the cancers associated with gastrointestinal tract." (PMID 33042126, 2020). "Our data were supported by studies showing that IL-22 drives NO-dependent dysplasia and DNA damage during a murine model of colitis-associated cancer." (PMID 32517114, 2020). "IL‐22 has been implicated in various pathological conditions including autoimmune, inflammatory, and infectious diseases and cancer." (PMID 31725949, 2020). "Apart from its protective characteristics, IL-22 is known to play a pathogenic role in autoimmune diseases, several cancers, and chronic liver damage." (PMID 28492497, 2017). "Interleukin-22 has been explored extensively in human cancer, but its functions and underlying mechanisms are incompletely understood." (PMID 28445985, 2017). "Clearly, the possible role that IL-22 plays in the development of other virus-associated cancers (e.g., human papilloma virus-induced cervical cancer) requires a better understanding." (PMID 27303405, 2016). "Different studies have shown that IL-22 expression is associated with pro-survival and proliferation in a number of human cancer cells." (PMID 25793261, 2015). "Although several studies have reported interleukin over-expression in K-ras positive cancer patients, this is the first time that IL-17, IL-22, and IL-23 are associated with K-ras-linked cancer stage-specific over-expression." (PMID 24040001, 2013). "LCN2 is associated with UC duration and cancer risk, which may be regulated by IL-17A, IL-22, and TNF-α." (PMID 40153427, 2025). "In addition, IL-22 secreted by primary cancer-associated fibroblasts (CAFs) significantly increased the proliferation of LC cell lines, an effect partially blocked with the application of an anti-IL-22 antibody." (PMID 40806452, 2025). "Whereas IL-22 from ILC3s has been linked with cancer promotion." (PMID 39309440, 2024). "Administration of L. reuteri suppressed keratinocyte chemoattractant (KC), Il22, Il6, Tnf, and IL1α gene expression in the colonic mucosa and reduced the amounts of proinflammatory, cancer-associated cytokines, keratinocyte chemoattractant, IL-22, and IL-6, in plasma." (PMID 36295796, 2022).
cancer (continued). "Furthermore, IL-22 can induce several genes that are associated with the maintenance of CRC cancer stem cells by promoting the STAT3 related pathway and epigenetic activation of these genes." (PMID 35154603, 2021). "However, in some cases, IL-22 signaling differs from reparative conditions and causes pathological conditions like inflammatory diseases and cancers due to dysregulation or increased levels like in chronic inflammation." (PMID 33042126, 2020). "IL-22-driven, iNOS-dependent DNA damage is associated with inflammation and cancer." (PMID 32670290, 2020). "Elevated levels of IL‐22 are reported in cancer patients and associated with poor survival rate." (PMID 31725949, 2020). "However, when cancer appears, inflammatory cells show a partly inter-related differentiation, which also causes elevated frequency of IL22+Th17 cells during the process." (PMID 26474968, 2015). "The IL-22 -429 C/T gene polymorphism has been associated with the risks for various cancers." (PMID 26598081, 2015). "Furthermore, under pathological conditions, intestinal dysbiosis due to antibiotic or other reasons may cause ILCs release cytokines such as IL-17 and IL-22, which may lead to chronic inflammation and cancer." (PMID 37304260, 2023). "Neutralization of IL-22 may improve disease control and quality of life for late stage disease patients by reducing metastasis, chemoresistance and inflammation associated with cancer." (PMID 33042126, 2020). "For example, IL-22 produced by tissue-resident iNKT cells or CD4+TRM cells promotes cancer metastasis at different stages." (PMID 39820040, 2025). "IL-1β, by inflammasome activation, is critical also to produce IL-22 by T helper 22 (Th22) cells, a cancer-promoting cytokine directly induced by some cancer cells." (PMID 38334625, 2024). "In a colitis-associated carcinoma mouse model, IL-22 induced epithelial signal transducer and activator of transcription 3 (STAT-3) phosphorylation and proliferation, thereby facilitating cancer development." (PMID 39309440, 2024). "Interleukin-22 (IL-22) produced by Th17 cells, and in humans also by Th1 cells, sustains the epithelial-to-mesenchymal transition and cancer cell migration." (PMID 38892411, 2024). "When TGF-β was present, Th17 cells played a pro-cancer role by secreting IL-17 and IL-22, while when IL-1βwas present, Th17 inducing CCL2 and CCL20 expression, DCs, and other immune cells were activated and recruited, resulting the inhibition of COAD." (PMID 39252305, 2024). "IL-22, IL-22R, and IL-22RA2 interactions play an important role in health and diseases and are involved in regulating cancer and homeostasis." (PMID 39769218, 2024). "In a breast and lung cancer murine experimental model, Th cells produce IL-22 that sustains cancer cells’ CD155 expression, inducing internalization of NK cells activating receptor CD226." (PMID 38892411, 2024). "IL-6 and IL-22, two cytokines that activate STAT3, enhanced XIAP in cancer cells, and such induction was attenuated in SMAD7-deficient cells." (PMID 39001432, 2024). "Soluble IL-22 binding protein derived from DCs can neutralized IL-22 and then suppress cancer progression by preventing the binding between IL-22 and IL-22R." (PMID 37063879, 2023). "We have recently shown that IL-22 plays a crucial role in the extravasation of cancer cells into the liver parenchyma." (PMID 37324022, 2023). "Secreted inflammatory cytokines in cancer cells, including IL-22, IL-6, IL-8, IL-4, IL-1β, HGF, IGF-1, EGF, G-CSF, TNF-α, VEGF, and IL-11, can confer the promotion of chemo- and radioresistance." (PMID 38140352, 2023). "Even though IL-22-secreting CAR T cells showed higher in vivo persistence, the main reason for the improved antitumoral activity was that IL-22 upregulates MUC1 expression in cancer cells, allowing a more effective recognition by CAR T cells." (PMID 36980536, 2023).
cancer (continued). "The action of NK cells can be modulated by IL-22 secreted by T lymphocytes which indirectly suppress the function of NK cells against cancer cells by modulating CD155 expression on the cancer cells’ surface." (PMID 36969193, 2023). "We have recently shown that IL-22 plays a crucial role in mediating the extravasation of cancer cells into the liver." (PMID 37324022, 2023). "Recombinant human interleukin-22 (IL-22), currently being developed as a cancer therapy, is a cytokine known for protecting the biological barriers, iron downregulation, and stimulation of adult neurogenesis, suggesting a beneficial role in SCZ." (PMID 37958780, 2023). "Overall, these results point to an innovative homeostatic control system contrary to previously discussed papers in which enhanced IL-22 secretion acts as a booster in cancer development." (PMID 36341381, 2022). "For example, as a fundamental mediator in inflammation, wound healing, and tissue regeneration, IL-22 also plays a pivotal role in the instigation of various cancers due to its pro-inflammatory and tissue repairing activity." (PMID 35268149, 2022). "Recent studies have elucidated the protumor role of Th22 cells and its lineage-specific cytokine IL-22 in different human cancers." (PMID 35669104, 2022). "In this study, we demonstrated the role of receptor of IL22 (IL22RA1) in cancers by studying the crosstalk between IL22RA1 and immune system." (PMID 35874683, 2022). "We show that IL-22 regulated pro-inflammatory pathways are involved in microbial recognition, cancer and immune cell chemotaxis; most prominently those involving CXCR2+ neutrophils." (PMID 36192482, 2022). "Chronic inflammation promotes cancer progression by increasing the production of pro-tumorigenic cytokines, mainly IL-6, IL-17A, IL-22 and IL-23, which activate NF-κB and STAT3 signaling pathways." (PMID 35387985, 2022). "Vitamin B5 is involved in the differentiation of some cytotoxic cells into CD8 + Tc22 cells that produce interleukin, e.g., IL-22, while in cancer treatment, it exhibits a treatment-enhancing action." (PMID 36687400, 2022). "IL-22 itself has a dual role in the development of cancer, as elucidated from a mouse model of inflammatory-driven CRC." (PMID 34868019, 2021). "Expression of both IL-22 and the IL-22 receptor was higher in cancer tissues compared to the control tissue, which correlated with poor prognosis." (PMID 34300224, 2021). "CAFs produce several cytokines such as IL-6, IL-11, and IL-22 and create a favorable environment for cancer." (PMID 34063828, 2021). "Th22 cells produce IL-22 which has been identified to promote migration and proliferation of cancer cells and resist apoptosis and chemotherapy." (PMID 33987104, 2021). "Regarding the overly pathological role of IL-22 in many cancer entities, it is quite likely that the fight against liver metastasis would equally benefit from an inhibition of IL-22." (PMID 33851257, 2021). "Recent studies indicate that interleukin 21 (IL-21) and interleukin 22 (IL-22) play an important role in the pathogenesis of cancer and cancer therapy." (PMID 34300224, 2021). "While IL-22 has advantageous effects, such as induction of epithelial cell proliferation and survival during tissue damage, uncontrolled IL-22 activity can promote cancer, as demonstrated in patients and mouse models." (PMID 33003458, 2020). "These ILCs produce IL-22 that promotes cancer development by inducing epithelial cell proliferation through phosphorylation of the Stat3 pathway; neutralization of IL-22 leads to abrogation of this process." (PMID 32670290, 2020). "Similar to our in vivo observations where IL‐22+/+/PyMT mice showed increased lung metastasis, IL‐22 treatment significantly increased both migration and invasion of cancer cells in vitro (P < 0.01)." (PMID 31725949, 2020).
cancer (continued). "The inhibition in malignant transition stage existed in IL‐22−/−/PyMT mice until the 14 weeks of age as acinar structures were still visible in primary tumors compared to solid sheets of cancer cells in control mice." (PMID 31725949, 2020). "Our results are in corroboration with these findings as the stimulation of IL‐22 effectively enhanced the in vitro migration and invasion of PyMT cancer cells." (PMID 31725949, 2020). "As IL‐22 is known to induce epithelial cell proliferation and a variety of cancer cells proliferate in response to IL‐22 treatment, we next tested our findings in vitro." (PMID 31725949, 2020). "In contrast to IL‐22−/−/PyMT mice, tumors in control mice progressed to the malignant transition stage and cancer cells appeared pleomorphic with moderate variation in nuclear morphology, size, and shape." (PMID 31725949, 2020). "It is possible that the generation of IL-22 in different stages of cancer development leads to different consequences." (PMID 32670290, 2020). "First, the presence of IL-22-producing Th17 and Th22 cells has been shown to increase in later cancer stages in CRC patients, and to be correlated with a poor prognosis." (PMID 32451418, 2020). "In GBM, the proinflammatory cytokines IL-17 and IL-22 have been identified as cancer-promoting molecules activating oncogenic STAT3 signaling, thereby protecting GBM cells from apoptosis, promoting GBM proliferation and enhancing invasion." (PMID 32069807, 2020). "Interleukin-22 (IL-22) is a key effector cytokine that plays a role in the pathogenesis of several inflammatory diseases including cancer." (PMID 31935914, 2020). "In this review, we summarize our current understanding of the involvement of IL-22 in liver injury, inflammation and cancer." (PMID 32760208, 2020). "IL-22 activates the STAT3 phosphorylation cascade in cancer cells and induces the expression of stem cell markers (SOX2, NANOG, and POU5F1), resulting in increased cancer stemness and tumorigenic potential." (PMID 32670290, 2020). "Bacteria induced colon cancer model shows an accumulation of ILCs where the depletion of IL-22 or CD90 reduced cancer development." (PMID 31024531, 2019). "Interleukin-22 (IL-22) is a T helper 17 (Th17) cells-secreted cytokine, it can promote invasion and metastasis of many cancers." (PMID 31528235, 2019). "We specifically investigated the mechanism by which IL-22 contributes to small intestinal tumorigenesis in the ApcMin/+ mouse model for cancer." (PMID 31770366, 2019). "IL-22 can increase cell proliferation and enhance cancer stemness by increasing expression of core stem cell genes, but it can also control elimination of damaged intestinal stem cells, preventing tumorigenesis." (PMID 31770366, 2019). "Most likely, IL-22 has anti-inflammatory and antimicrobial effects that protect from cancer, while at the same time IL-22 supports the proliferation of epithelial cells promoting the development of cancer." (PMID 29967613, 2018). "The bioassay was based on inhibition by IL-22BP of IL-22-induced STAT3 phosphorylation in the A549 cancer cell line." (PMID 30619294, 2018). "Colonic IL-22 (a cytokine that promotes proliferation of cancer cells) levels were lower (p = 0.057, Student’s t-test) in L. casei BL23-treated mice compared to controls." (PMID 29209314, 2017). "Knockdown of HK2 by siRNA attenuated the promotion of IL-22 on glucose consumption and lactate production, indicating that HK2 is a functional downstream target of IL-22 in facilitating aerobic glycolysis of cancer cells." (PMID 28445985, 2017). "The weak SOCS3 mRNA induction by IL-22 was confirmed in all the cancer cell lines examined (n = 2 for BCC and n = 5 for SCC), as compared to healthy keratinocyte strains (n = 5)." (PMID 28445952, 2017).
cancer (continued). "In this study, we tested the effects of a newly-developed peptide, mimicking KIR and ESS domains of SOCS3 protein, in cultured transformed and healthy keratinocytes, following IL-22 stimulation, and in a cancer mouse model of SCC." (PMID 28445952, 2017). "In this study, we identified SOCS3 as the key SOCS family member involved in the suppression of IL-22 signaling in healthy and transformed cultured keratinocytes, and in vivo in a cancer mouse model of SCC." (PMID 28445952, 2017). "Interleukin-22 is deregulated in cancer conditions, tissue regeneration regulation function is transformed into the driving cancer development." (PMID 27670445, 2016). "IL-22 in cancer cells can promote activation of the transcription factor STAT3 and expression of the histone 3 lysine 79 (H3K79) methyltransferase DOT1L." (PMID 25590298, 2015). "For example, the heightened production of IL-22 by Th17/Th22 cells in patients with pancreatic or lung cancer correlates with poor prognosis and survival." (PMID 24987392, 2014). "The levels of IL-17, IL-22 and IL-23 in cancer patients and healthy controls were determined using human interleukin ELISA Immunoassay, Western Blot, and RT-PCR techniques." (PMID 24040001, 2013). "Although IL-22 appears to act variously in different carcinoma cells, there is little knowledge on the potential roles of IL-22 in OSCCs." (PMID 22922995, 2012). "In the context of cancer, IL-22 plays a dual role; while it could be beneficial in supporting mucosal defense, excessive IL-22 signaling has been implicated in colorectal carcinogenesis." (PMID 40944286, 2025). "There is controversial information regarding the prognostic significance of IL-22 in cancer." (PMID 40806452, 2025). "IL22 has been shown to promote cancer formation in both the colon and pancreas." (PMID 38339226, 2024). "However, in cancer, IL-22RA2 was found to be decreased, which would then allow IL-22 tumorigenic effects." (PMID 39769218, 2024). "IL-22 is a cancer-promoting cytokine that is elevated in various cancers." (PMID 38643339, 2024). "After exposure to multiple inflammatory microenvironmental factors, molecules such as IL-4, IL-6, IL-8, IL-17α, IL-22, IL-23, IL-33, and interferon-γ, induce complex genetic/molecular changes in precancerous stem cells (pCSC) to gradually form cancer stem cells (CSCs)." (PMID 39073546, 2024). "Although IL-22 can have many beneficial functions such as promoting intestinal integrity, supporting the mucosal barrier function and protecting against genotoxic stress, it can also act on cancer cells directly and fuel cancer progression." (PMID 37324022, 2023). "Similarly, it was found that the IL-22 secreted by cancer-related fibroblasts elicits a protumor effect on NSCLC cell lines through the PI3K-Akt-mTOR signal pathway." (PMID 35669104, 2022). "In particular, it has been described that IL-22-producing ILC3s may play a crucial role in cancer related to Helycobacter hepaticus-induced colitis (H.hepaticus + AOM model)." (PMID 36341381, 2022). "IL-22 and IL-22R1 were indeed reported to be over-expressed in different types of cancers." (PMID 35422799, 2022). "Similarly, the activation of the IL-22/IL-22R1 cascade reported in different chronic settings was involved in immune protection but overlapped with hyper-inflammatory conditions and even cancers." (PMID 35422799, 2022). "IL22 is multifunctional and involved in various diseases including cancer." (PMID 35874683, 2022). "IL-22 promotes cancer cell migration and invasion via STAT3, ERK, JNK, and Akt pathways." (PMID 34063828, 2021). "However, most details of IL-22-induced apoptosis in response to DNA damage in the intestinal tract and its anti-cancer effects are yet to be clarified." (PMID 34759916, 2021). "Most recently, however, IL-22 has been shown to play a key role in the control of genotoxic damage induced by carcinogens in colon epithelial stem cells, thereby limiting mutagenesis and cancer outgrowth." (PMID 34296212, 2021).